FOS (Fos proto-oncogene, AP-1 transcription factor subunit)
Diseases named in the same sentence as FOS in open-access papers (continued):
Sharing a sentence is not in itself a finding about the gene and the disease.
thyroid cancer (13 papers, 2008 to 2025). "Moreover, FOS and JUN expression alterations in FTC, along with SFN upregulation in PTC, further highlight these genes as promising diagnostic candidates for specific thyroid cancer subtypes." (PMID 40722651, 2025). "Let us analyze what measure of regulation is the most informative and use the examples of FOS and KIT (another gene down-regulated in thyroid cancer)." (PMID 32887258, 2020). "A strong inducer of GABPB expression is FOS and T-5224, which is a new small molecule inhibitor of FOS, selectively suppress TERT expression in thyroid cancer cells carrying TERT promoter mutations but not in wild-type TERT cells." (PMID 38033865, 2023). "The observed down-regulation of FOS in PTC confirms the findings of some groups but contradicts its frequent (however not 100%) up-regulation reported by another group in 40 patients with thyroid cancer and 20 with benign thyroid diseases." (PMID 32887258, 2020). "Furthermore, a recent study demonstrates that the loss of CBX7 observed in thyroid carcinomas leads to a negative or positive regulation of key genes involved in tumorigenesis, as the AP1 complex members FOS and FOSb, and the chemokine SPP1, respectively." (PMID 25595895, 2015).
bone tumors (12 papers, 2014 to 2023). "Overall, our findings reveal a human bone tumour defined by mutations of FOS and FOSB." (PMID 29858576, 2018). "Studies had shown that FOS was closely related to the pathogenesis of bone tumors in mice." (PMID 33941222, 2021). "The aim of this study was to evaluate whether the recently found FOS and FOSB rearrangements can be used as an auxiliary diagnostic tool in routine bone tumor diagnosis." (PMID 31768625, 2020). "This shifts our understanding of FOS/AP-1 dysregulation in human bone tumours." (PMID 29858576, 2018).
endometrial cancer (12 papers, 2014 to 2025). Primary or metastatic malignant neoplasm involving the endometrium (mucous membrane that lines the endometrial cavity). "FOS plays a significant role in endometrial cells’ proliferation and its overexpression is associated with a poor prognosis of endometrial carcinoma." (PMID 32575462, 2020). "The estrogen signaling pathway, which is highly associated with the development of endometrial cancer, showed enrichment of four differentially expressed ARGs (ITPR1, FOS, PRKCD, and BCL2)." (PMID 33109128, 2020). "We therefore hypothesized that MAPK signaling promotes the appreciation of endometrial carcinoma cells by increasing glucose uptake, regulation of c-FOS and cJUN proteins, and being activated by estrogen." (PMID 35672846, 2022). "MicroRNA-101 targets EZH2, MCL-1 and FOS to suppress proliferation, invasion and stem cell-like phenotype of aggressive endometrial cancer cells; MicroRNA-101 inhibits cell progression and increases paclitaxel sensitivity by suppressing MCL-1 expression in human triple-negative breast cancer." (PMID 32309578, 2016). "The microRNA-101-EZH2/MCL-1/FOS axis is a potential therapeutic target for endometrial cancer." (PMID 25153722, 2014). "Although another study has indicated that miR-101 can suppress proliferation, migration and invasion, and stem cell-like phenotype of aggressive endometrial cancer cells, at least through targeting EZH2, MCL-1 and FOS." (PMID 29333128, 2017).
rheumatoid arthritis (12 papers, 2013 to 2024). A chronic, systemic autoimmune disorder characterized by inflammation in the synovial membranes and articular surfaces. "FOS is also a regulatory enhancing the proliferation of lymphocytes in rheumatoid arthritis patients." (PMID 38818568, 2024). "In macrophages from JD (MAPinf) cows, we also observed a reduction of FOS and its enrichment in the rheumatoid arthritis pathway, suggesting a role of this master transcriptional regulator in immunoregulatory and inflammatory processes." (PMID 34975852, 2021). "Among PSA T and NK cells, we also observed a downregulation of AP-1 transcription factors (JUN, JUNB, JUND, FOS) and regulators of activation (TNFAIP3, DUSP1) along with the upregulation of S100A11, a calcium-binding protein associated with rheumatoid arthritis." (PMID 35309349, 2022). "For example, rs3184504, a nonsynonymous SNP in SH2B3 that was associated in GWAS with BP, coronary heart disease, hypothyroidism, rheumatoid arthritis, and type 1 diabetes, is a trans-eQTL for 6 of our 34 BP signature genes from the meta-analysis (FOS, MYADM, PP1R15A, TAGAP, S100A10, and FGBP2)." (PMID 25785607, 2015).
cardiac hypertrophy (11 papers, 2011 to 2025). "Finally, mice deficient in Atf3 which encodes transcription factor 3 (ATF3), a partner protein of FOS, exhibited fibrosis and cardiac hypertrophy in response to pressure overload, suggesting an important transcriptional role for Atf3 in the cardiovascular system." (PMID 36736425, 2023). "This is important because FOS expression is known to be increased during cardiac hypertrophy and heart failure." (PMID 32296036, 2020). "FOS and JUN transcription factors are thought to be among the first set of genes to be expressed in the context of pathological cardiac hypertrophy, and EP300 has been associated with cardiomyocyte enlargement." (PMID 28797094, 2017). "These include MYC and FOS which have been shown to play a key role in cell proliferation and transformation and are also involved in the regulation of cardiac hypertrophy." (PMID 25255322, 2014). "Literature text-mining using GeneCards Version 3 reveals that FOS is involved in cardiac hypertrophy." (PMID 22136190, 2011). "Research suggests that high expression of FOS may initiate the expression of myocardial structural protein genes, acting as a trigger for myocardial hypertrophy." (PMID 41300325, 2025). "Histone H3 lysine K27 acetylation on the DNA promoter promotes FOS transcription, cardiomyocyte fibrosis and inflammation through the FOS/AP-1 pathway, however, SIRT3 participates in histone H3DE deacetylation, which can inhibit the occurrence of cardiac hypertrophy." (PMID 37507372, 2023).
lung adenocarcinoma (11 papers, 2017 to 2025). A carcinoma that arises from the lung and is characterized by the presence of malignant glandular epithelial cells. "Mechanistically, the EGFR signaling pathway promoted the expression of miR-651-5p by activating the transcription factor Fos proto-oncogene (FOS) in EGFR-mutant lung adenocarcinoma cell lines." (PMID 40002895, 2025). "EGF treatment caused the expected transient induction of FOS in these cells and also a more sustained activation of EINCR1 in these lung adenocarcinoma cells." (PMID 28732076, 2017). "In lung adenocarcinoma, high expression of CCL20, IL23A, MMP1 and MMP3 was significantly associated with poor patient prognosis, whereas high expression of FOS, HLA-DPA1, HLA-DPB1, HLA-DQA1, HLA-DQB1 and HLA-DRA was significantly associated with improved patient prognosis." (PMID 40016789, 2025). "Based on TCGA and GTEx databases, the expression levels of FOS, GADD45B, and EGR1 in liver hepatocellular carcinoma (LIHC) and lung adenocarcinoma (LUAD) were lower than those in normal samples." (PMID 37405258, 2023). "We noticed that in lung adenocarcinoma samples, many EGF-inducible genes, including FOS and IER2 are downregulated whereas EINCR1 expression is generally upregulated." (PMID 28732076, 2017). "To further explore this phenomenon, we analysed the expression of EINCR1 and two EGF-inducible genes, FOS and FOSB across the lung adenocarcinoma samples in the TCGA-LUAD dataset." (PMID 28732076, 2017).
memory impairment (11 papers, 2011 to 2024). "Specifically, is a T21 induced memory impairment associated with reduced hippocampal c-FOS expression." (PMID 36311860, 2022). "When trying to determine the root of a memory impairment, assessing neuronal activation with c-FOS is useful." (PMID 36311860, 2022). "Our hypothesis is that the memory impairment induced by a T21 light dark cycle is accompanied by attenuated c-FOS expression in all hippocampal subfields." (PMID 36311860, 2022). "Quantifying c-FOS expression in the hippocampus is a good step for investigating a memory impairment because it will provide information on whether the effect is due to less neurons being recruited during learning or memory retrieval." (PMID 36311860, 2022). "In the current study, we will use a T21 paradigm that produces memory impairments in the MWT, and then assess c-FOS expression in the dentate gyrus, CA1, and CA3 regions of the hippocampus after the probe trial." (PMID 36311860, 2022). "In the current study, we rule out reduced c-FOS in hippocampal sub-regions as an explanation for memory impairments that are induced by circadian rhythm disruption." (PMID 36311860, 2022).
asthma (10 papers, 2012 to 2025). "Interestingly, numerous Ca2+-dependent transcription factors like c-FOS, nuclear factor of activated T cell (NFATC1), and cAMP response element–binding protein (CREB1) as well as the asthma-associated protein ORMDL3 were downregulated in the NCLX KD HASMCs." (PMID 35841929, 2022). "In our study, the expression of transcription factors, including phosphorylated NF-κB, c-FOS and c-JUN, was higher in patients with severe asthma than in those with mild/moderate asthma or in healthy controls." (PMID 32112175, 2020). "The results showed gradually elevated expression of p-NF-κB, p-c-FOS, and p-c-JUN from normal subjects to patients with mild/moderate asthma to patients with severe asthma (p < 0.01 severe asthma vs. normal; p < 0.05 severe asthma vs. mild/moderate asthma)." (PMID 32112175, 2020). "Among the top genes are ones that have been previously related to asthma (e.g., APOE, CHI3L1, EGR1, MYH11, OXTR, SERPINB2, SOCS3) and corticosteroid-resistant asthma (e.g., FOS) though not necessarily in humans or via changes of the ASM." (PMID 26207385, 2015).
breast tumor (10 papers, 2008 to 2023). "In a previous study, reduced FOS gene expression levels were associated with high histologic grade in breast tumors." (PMID 18928543, 2008). "However, expression of FOS, a pro-proliferative transcription factor, which has been validated in breast tumour samples and is highly expressed in relapse samples and treatment failures, was found to be downregulated at all time points." (PMID 36661191, 2023). "In an independent series of breast tumor samples (19 nonrelapsing and 14 relapsing), reduced expression of ESR1/ERα, IGFBP4, SNCG, BCL2, and FOS was observed in the relapsing group and was associated with a shorter overall survival." (PMID 18928543, 2008).
epithelioid hemangioma (10 papers, 2018 to 2025). A hemangioma characterized by the presence of epithelioid endothelial cells. "VIM, located on chromosome 10p13, encodes vimentin and has been described in fusions with FOS in a subset of epithelioid hemangioma." (PMID 32461620, 2020). "Chromosome translocations involving the FOS gene have been identified as a genetic hallmark of epithelioid hemangioma, whilst rearrangements involving FOSB have been detected in pseudomyogenic hemangioendothelioma and in a subset of epithelioid hemangioma, defined as cellular/atypical variant." (PMID 33114111, 2020). "Identical rearrangements in FOS were previously detected in epithelioid haemangioma, where these led to truncation of the FOS protein in the C-terminal domain, causing increased protein stability due to impaired degradation." (PMID 41424327, 2025). "Epithelioid hemangioma (EH) is classified as a benign tumor according to the 2018 ISSVA classification, and the causal gene for vascular abnormalities is recognized to be FOS." (PMID 39061195, 2024). "Identical to FOS-rearranged epithelioid hemangioma, the translocations involve various genes or intergenic regions and lead to a premature stop codon, at or early after the break points that always involve exon 4 of FOS." (PMID 31768625, 2020). "FOS gene rearrangements are present in the majority of bone and soft tissue epithelioid hemangiomas but are rare in cutaneous epithelioid hemangiomas." (PMID 32316685, 2020). "Of interest, recent report about frequent FOS gene rearrangements in cases of atypical epithelioid hemangiomas has been described and whether such rearrangements can be detected in cases of CEAN have yet to be investigated." (PMID 30103782, 2018).
myocardial infarction (10 papers, 2020 to 2026). Gross necrosis of the myocardium, as a result of interruption of the blood supply to the area, as in coronary thrombosis. "FOS upregulation is observed in some cardiovascular diseases, including viral myocarditis, acute myocardial infarction, heart failure, and abdominal aortic aneurysms, indicating a potential link between FOS and these pathophysiologic processes." (PMID 34858201, 2021). "Silencing XIST expression improved cell viability and suppressed apoptosis in vitro and inhibited myocardial infarction by reducing the level of c-FOS and apoptosis-related proteins in vivo." (PMID 32315985, 2020). "In conclusion, our present study reveals that lncRNA XIST is integrated into the machinery of myocardial infarction, and that XIST can affect myocardial infarction and cardiomyocyte apoptosis by regulating the expression of FOS." (PMID 32315985, 2020). "MiR-101a-3p reduce myocardial infarction and protects myocardial cell apoptosis through targeting FOS in vivo and in vitro." (PMID 32315985, 2020). "For example, a PMO-TSB targeting the miR-101a-3p binding site on XIST could restore miR-101a-3p availability to suppress FOS, thereby reducing cardiomyocyte apoptosis following myocardial infarction." (PMID 41601966, 2026). "lncRNA Xist, which positively mediates PDE4D expression via interacting miR-130a-3p and targets miR-101a-3p through regulating FOS, promotes myocardial infarction development and cell apoptosis, and inhibits cell proliferation though the miR-130a-3p/PDE4D aixs and miR-101a-3p/FOS aixs." (PMID 34178980, 2021). "XIST regulates FOS expression and the consequent myocardial infarction through miR-101a-3p." (PMID 32315985, 2020). "Based on this part of the experimental results, we concluded that decreasing XIST expression could protect mice from myocardial infarction and cardiomyocyte apoptosis in some degree by down-regulating the expression of c-FOS and apoptosis-related proteins." (PMID 32315985, 2020). "Increased levels of XIST RNA were reported in a model of myocardial infarction, where sequestration of miR-101a-3p by XIST de-repressed transcription factor FOS and increased cardiomyocyte apoptosis." (PMID 41601966, 2026). "In the treatment of myocardial infarction, we have obtained key targets of Yixinyin, which are ALDH2, C5AR1, FOS, IL1B, TLR2, TXNRD1." (PMID 34799616, 2021). "In the present study, we revealed the lncRNA-miRNA-mRNA axis that participate in myocardial infarction, which was the XIST-miR-101a-3p-FOS axis." (PMID 32315985, 2020).
myopia (10 papers, 2007 to 2025). "We failed to confirm with the replication sample set the initial significant association of FOS haploypes with high myopia in the discovery sample set." (PMID 23637909, 2013). "In this study, we found that both photoreceptor cells and RGC cells underwent apoptosis at 4 and 6 weeks of myopia, while knockdown of FOS significantly reduced apoptosis in the retina and inhibited myopia progression to some extent." (PMID 40610752, 2025). "Of all the 123 possible sliding windows, 2 windows of the FOS gene and 13 windows of the VIPR2 gene displayed significant association (Paemp<0.05) with high myopia even after correction for multiple comparisons (n = 123) by permutation test." (PMID 23637909, 2013). "In addition, we also found that knocking down retinal FOS expression in myopia can reduce damage to the visual path, that is, inhibit TSD." (PMID 40610752, 2025). "In the present study, we found that the apoptosis of RGCs in myopia leads to structural and functional impairments in the downstream visual pathway and that knocking down FOS can inhibit the apoptosis of the retina and alleviate damage to the downstream visual pathway." (PMID 40610752, 2025). "Therefore, we selected EGR1, FOS, JUN, VIP and VIPR2 as functional candidates and investigated their potential association with high myopia." (PMID 23637909, 2013). "Knocking down FOS expression inhibited RGC apoptosis, inhibited damage to downstream pathways and slowed the progression of myopia." (PMID 40610752, 2025). "While the progression of myopia was enhanced through the treatment of lipopolysaccharide (LPS) or peptidoglycan (PGN), the expression level of IL-6, TNF-α, c-FOS, and nuclear factor κB increased." (PMID 28828383, 2017). "Furthermore, our research results also indicate that when AAV knockdown of FOS is used to inhibit retinal apoptosis and alleviate TSD during myopia induction, the degree of LTD is inhibited to a certain extent compared with the myopia group alone." (PMID 40610752, 2025). "In addition, previous research showed that myopia progression was slowed down by cyclosporine A (CSA) and CSA treatment further reduced the expression of IL-6, TNF-α, c-FOS, and NF-κB in the eye." (PMID 34285659, 2021). "EGR1, JUN, FOS and VIP are unlikely to be important in predisposing humans to high myopia." (PMID 23637909, 2013).
Parkinson disease (10 papers, 2021 to 2025). A progressive degenerative disorder of the central nervous system characterized by loss of dopamine producing neurons in the substantia nigra and the presence of Lewy bodies in the substantia nigra and locus coeruleus. "Subsequent investigation in pain processing regions of the brainstem affected in early Parkinson’s disease, identified a significant reduction in c-FOS+ detections in the RMg of 6-OHDA lesioned rats compared to sham, with no change in the LC." (PMID 37100804, 2023). "Previous studies have reported a decrease in c-FOS in the subthalamic nuclei of Parkinson’s patients." (PMID 36292747, 2022). "Genes in the low-expression cohorts of DUSP1, FOS, and NFIL3 were mainly enriched in oxidative phosphorylation, as well as Parkinson's disease." (PMID 38384585, 2024).
skin cancer (10 papers, 2009 to 2022). "In the mouse model, FOS-dependent PDPN expression was observed in mouse skin tumors induced by 12-O-tetradecanoylphorbol-13-acetate (TPA)." (PMID 35159384, 2022).
Alzheimer disease (9 papers, 2015 to 2025). A progressive, neurodegenerative disease characterized by loss of function and death of nerve cells in several areas of the brain leading to loss of cognitive function such as memory and language. "Although it has been reported to be a biomarker for Alzheimer’s disease and type 2 diabetes, there are many studies that have explored the biomarker status of FOS in NAFLD, NASH, and even fatty liver disease." (PMID 33927635, 2021).
fibrosis (9 papers, 2020 to 2025). the formation of excess fibrous connective tissue in an organ or tissue in a reparative or reactive process. "SIRT3 mediated the FOS inhibition through histone H3 deacetylation prevents cardiac fibrosis and inflamm-aging." (PMID 40060963, 2025). "Sirtuin3 (SIRT3), a deacetylase, regulates the FOS/AP-1 pathway to alleviate myocardial fibrosis and inflammation." (PMID 40520937, 2025). "At the same time, miR-29b-3p mitigates cardiac fibrosis following infarction by directly targeting FOS." (PMID 39712244, 2024). "FOS, a gene critical for monocyte and macrophage function, showed that SIRT3-mediated inhibition of FOS through histone H3 deacetylation prevents cardiac fibrosis and inflammation." (PMID 35600966, 2022). "SIRT3 prevents cardiac fibrosis and inflammation via regulating the FOS/AP-1 pathway." (PMID 37196115, 2023). "Hence, it is plausible that the release of TFs FOS, FOSB, and JUNB by C6 S100A4+ SMCs contributes to exacerbating cardiomyopathies, potentially through the induction of cardiac fibrosis and inflammation." (PMID 40717095, 2025).